TF (transferrin)
Diseases named in the same sentence as TF in open-access papers (continued):
Sharing a sentence is not in itself a finding about the gene and the disease.
kidney disease (18 papers, 2015 to 2025). "The urinary TF was suggested to be used as a diagnostic marker of early diagnosis of renal disease in Stage I of CKD cat since leakage of urinary TF in urine precedes leakage of urinary ALB, and their sensitivity and specificity were higher than those of plasma CR concentration." (PMID 36855344, 2023). "Patients with kidney disease often experience high concentrations of iron within their renal tubules due to the increased filtration of iron and iron-containing proteins, such as hemoglobin, transferrin, and neutrophil gelatinase-associated lipocalin (NGAL) in the glomeruli." (PMID 38001784, 2023). "Although serum ferritin and transferrin saturation are the recommended iron indices by the Kidney Disease Outcome Quality Initiative, they are indirect indicators of iron status." (PMID 30013785, 2018). "In accordance with previous studies, we observed increased urine IgG and transferrin in a subgroup with moderately increased albuminuria and both proteins were specific markers of kidney disease." (PMID 30158836, 2018). "Two validated changing proteins, transferrin and the alpha-1-antiproteinase, are two of the most common markers of renal diseases." (PMID 25789206, 2015). "The level of transferrin in the plasma decreases in conditions of liver and kidney diseases." (PMID 27303789, 2016). "With the progression of kidney disease, the production of transferrin in the liver is reduced, and in advanced stages of CKD, transferrin levels are reduced by 30%." (PMID 33025407, 2021). "The key finding of the present study is that urinary transferrin was significantly related with subclinical atherogenesis, particularly in patients with diagnosis of t2DM, who had not developed renal disease yet." (PMID 34743740, 2021). "Our findings indicate that the widely available markers such as serum cystatin C, urine IgG, transferrin, and NGAL may help in early assessment of kidney disease in T2DM patients, although large prospective studies are needed to confirm the conclusion." (PMID 30158836, 2018). "Widely available markers, serum cystatin C, urine IgG, transferrin, and NGAL, may help in early assessment of kidney disease in T2DM patients; however, large prospective studies are needed to confirm the conclusion." (PMID 30158836, 2018).
iron metabolism disorders (16 papers, 2015 to 2026). "Finally, at the neuronal level, the increased iron deposition in the brain of PD patients may be due to transferrin transfer, iron citrate diffusion, increased iron influx and impaired iron dysfunction caused by intracellular iron metabolism disorders." (PMID 31117957, 2019). "This study found that patients with PLA had significantly altered iron metabolism disorders, manifested by decreased serum iron, TF and TIBC, while ferritin is significantly elevated." (PMID 41280746, 2025). "In people with iron metabolism disorder, Fe3+ accumulates by binding to transferrin (TF) and enters the cell through transferrin receptor-mediated endosomes." (PMID 34178024, 2021). "Notably, they had significant iron metabolism disorders, such as, decreased serum iron, TF and TIBC, and increased ferritin." (PMID 41280746, 2025). "The Ferritin, transferrin, and transferrin saturation levels are normal, but the iron accumulation in the basal ganglia is a relevant finding, suggesting that despite normal blood levels, there might be an iron metabolism disorder at the mitochondrial level." (PMID 40597358, 2025). "The data showed that hepcidin correlated positively with Hgb, AGP, hs-CRP, TAC, iron conc., ferritin, transferrin saturation (%), and negatively with TBIS, sTfR, and TOS as biomarkers of metabolic iron disorders in ID, IDA, and overloaded subjects, respectively." (PMID 38102707, 2023). "In adolescents with iron disorders, positive correlations were found between the expression of miRNAs; miR-146a and miR-125b, and miR-122 and hepcidin, ferritin, iron, transferrin saturation, TAC, and haemoglobin; conversely, negative correlations were reported with sTfR, TIBs, AGP,hs-CRP, and TOS." (PMID 38102707, 2023). "However, the expression of TF and TFRC was decreased at 24 h.p.i., and it may affect iron transport and eventually lead to iron disorder in cells." (PMID 35715835, 2022).
neurodegenerative disease (12 papers, 2010 to 2026). A disorder of the central nervous system characterized by gradual and progressive loss of neural tissue and neurologic function. "The TF genes FSOL2, MESI2, NEF2L2, and PRDM2 have been reported to be associated with neurodegenerative diseases." (PMID 32149119, 2020). "The potential relationship between these TF genes and neuronal differentiation or neurodegenerative diseases has been reported in previous studies." (PMID 32149119, 2020). "The P570S (TF, C1C2) genetic variant has been assessed in the context of iron balancing and in several neurodegenerative diseases, but a synergistic effect of the HFE and TF genes also suggests possible gene-gene and gene-environment interactions." (PMID 29518107, 2018). "Very little data exists regarding the role of anti-transferrin antibodies in neurodegenerative diseases." (PMID 27090083, 2016). "The development of different neurodegenerative diseases is associated with alterations of the intracellular transport of iron and heavy metals, principally mediated by Divalent Metal Transporter 1 (DMT1), responsible for Non-Transferrin Bound Iron transport (NTBI)." (PMID 31231185, 2019). "Moreover, the TF genes FSOL2, KLF11, and NEF2L2 play essential roles in the neurodegenerative diseases." (PMID 32149119, 2020). "The results of the present study with regard to certain oxidative stress-related proteins (transferrin, ferritin, HO1, and NQO1) suggest that JGT could help to reduce neuroinflammation-related events and neuronal cell death in some neurodegenerative diseases." (PMID 30891075, 2019). "Despite the unquestionable key role that iron genes have on neurodegenerative disease pathogenesis, iron SNPs have not been widely investigated, with the only exception of HFE and TF polymorphisms that are reported in dedicated meta-analyses." (PMID 29518107, 2018).
inflammation (8 papers, 2005 to 2025). Aberrant reaction of the microcirculation characterized by movement of fluid and leukocytes from the blood into extravascular tissues. "Previous studies have shown that elevated FcγRIII and TF expression, along with reduced TM levels, are markers of endothelial inflammation and damage." (PMID 39409186, 2024). "This aligns with previous studies showing that elevated FcγRIII and TF expression and reduced TM serve as indicators of endothelial inflammation and damage, respectively." (PMID 39409186, 2024). "As pulmonary inflammation stimulates TF expression and TF modulates immune responses, we aimed to elucidate its impact on ALI." (PMID 28509332, 2017). "There is mounting evidence indicating that TF plays a pivotal role in the procoagulant response in the pulmonary compartment during various forms of pulmonary inflammation and lung injury." (PMID 22195278, 2012). "In this cohort there were no cases of overt systemic inflammation according to maternal CRP, nor were ferritin and transferrin concentrations significantly correlated with CRP." (PMID 16000177, 2005).
neurological diseases (7 papers, 2019 to 2025). "Hence, we report a magnetic transferrin nanoparticles (MTNs) assay to isolate brain-derived blood exosomes in neurological diseases." (PMID 36797805, 2023).
brain diseases (5 papers, 2016 to 2025). "From this study, we can propose conformational details of the mechanism of pH-dependent iron release from transferrin, including a monoferric intermediate state, which will have important biomedical research impacts on the transport of iron or ligands against brain diseases." (PMID 34948188, 2021). "Then transferrin (TF) was introduced into liposomes through covalent modification to prepare TF Rut liposomes, indicating that TF Rut lip has brain targeting, which may improve the efficacy of Rut in the treatment of brain diseases." (PMID 40529506, 2025).
heart disease (5 papers, 2016 to 2024). "Whether these TF genes are expressed or play roles in heart disease requires further analysis." (PMID 27635320, 2016). "On the other hand, all thalassemic patients with heart disease found that they were plasma NTBI positive and had a plasma transferrin saturation above 70%8." (PMID 28287621, 2017).
adenocarcinoma (4 papers, 2015 to 2025). A common cancer characterized by the presence of malignant glandular cells. "The results of LDH assay showed that cerium alone and in the presence of transferrin was significantly increased in cell survival of adenocarcinoma cells (p=0.001)." (PMID 26664465, 2015). "In conclusion, this study can describe cerium and transferrin effect on cell growth inhibition in adenocarcinoma cells, but the actual mechanism of action remains unclear, which will need further studies to be understood." (PMID 26664465, 2015).
hematological disease (4 papers, 2011 to 2022). "CEBPA and c-MYC genes belong to TF and play an essential role in hematologic malignancies development." (PMID 33170359, 2020).
infectious disease (4 papers, 2012 to 2021). A disorder directly resulting from the presence and activity of a microbial, viral, or parasitic agent in humans. "Bacterial endotoxin LPS, immune complexes and many other factors elaborated in various infectious diseases are shown to induce procoagulant TF expression in monocytes/macrophages and the endothelium, which under normal healthy state do not express TF." (PMID 23029190, 2012).
kidney (4 papers, 2019 to 2024). "Moreover, TF mRNA, an NFκB-dependent product, increased with a concomitant increase in TF protein in glomerular capillary tufts and within tubular epithelium implying that SAA can stimulate procoagulant activity through an NFκB-dependent pathway, a feature of several kidney pathologies." (PMID 30899260, 2019).
movement disorder (4 papers, 2017 to 2025). Neurological conditions resulting in abnormal voluntary or involuntary movement, which may impact the speed, fluency, quality and ease of movement. "BPAN is a movement disorder with Non Transferrin Bound Iron (NTBI) accumulation in the basal ganglia as common hallmark between NBIA classes." (PMID 28261264, 2017). "Simple blood analysis, including serum iron, ferritin, and transferrin saturation levels, should be investigated in patients with a movement disorder of unknown etiology." (PMID 40941762, 2025). "Blood analysis, including serum iron, ferritin, and transferrin saturation levels, should be investigated in patients with movement disorders of unknown etiology or with iron deposition on neuroimaging." (PMID 40941762, 2025).
gastrointestinal disease (3 papers, 2018 to 2024). A disease that occurs in the gastrointestinal system, excluding the hepatobiliary system. "SSR4 was first identified in congenital disorders of glycosylation patients, and SSR4 mutation leads to gastrointestinal diseases and abnormal glycosylation of serum transferrin levels in congenital disorders." (PMID 39872215, 2024).
liver (3 papers, 2021 to 2025). "Increasing evidence suggests that postoperative ENN also promotes postoperative bowel motility and increases TP and transferrin levels in patients with gastrointestinal tumors." (PMID 41393952, 2025).
skin disorder (3 papers, 2022 to 2023). Any deviation from the normal structure or function of the skin or subcutaneous tissue that is manifested by a characteristic set of symptoms and signs. "We built a TF-miRNA-mRNA regulatory network to reveal the novel mechanism (miR-21-PPARA-NCOA6) of dysregulated keratinocyte proliferation, differentiation, and migration in diabetic skin, which may provide new insights into the susceptibility of skin disorders in T2DM patients." (PMID 35477946, 2022).
genetic disease (2 papers, 2008 to 2017). "A similar analysis in human revealed 35 TF genes linked to various diseases and genetic disorders." (PMID 18752680, 2008). "Genetic disorders linked to human TF genes conserved among nematodes, fly, mouse, and human." (PMID 18752680, 2008).
peripheral neuropathy (2 papers, 2014 to 2017). A disorder affecting the peripheral nervous system. "Similarly, transferrin levels have been associated with peripheral neuropathy after bariatric surgery, which has been shown to disrupt iron homeostasis." (PMID 25144566, 2014).
retinopathies (2 papers, 2022 to 2025). "We previously showed in multiple retinopathy models that a local intraocular TF administration preserved both retina morphology and function by controlling iron-induced oxidative stress and through iron-unrelated pathways, without any side-effects." (PMID 36361544, 2022). "Multiple nodes, such as TF, TFR, DMT1, FT, and FPN1, can regulate iron levels; however, these proteins exhibit distinct expression patterns across retinopathies, and it is difficult to find “universal” intervention nodes." (PMID 41394869, 2025).
connective tissue disorder (1 paper, 2015). A disease involving the connective tissue. "We also find evidence for activation of multiple other inflammatory and connective tissue-disorder pathways mediated through pro-inflammatory TF genes such as STAT3, IRF1 and IRF7, CEBPB and SMAD4." (PMID 26202100, 2015).
neurodevelopmental disorder (1 paper, 2022). A behavioral and cognitive disorder with onset during the developmental period that involves impaired or aberrant development of intellectual, motor, or social functions. "In our study, Hb levels and HCT in ASD patients were slightly lower than in the control group, while serum levels of iron and transferrin were higher than in patients with other neurodevelopmental disorders, although the difference was not statistically significant." (PMID 35409689, 2022).
TF also shares sentences with these, for which no sentence is quoted: chronic heart failure (7 papers); dementia (7); alcohol (6); Anxiety (6); Parkinson’s (6); acute myocardial infarction (5); hepatitis B (5); hyperlipidemia (5); unstable angina (5); Hepatic steatosis (4); acute lymphoblastic leukemia (3); arthropathy (3); cardioembolic stroke (3); cataract (3); chronic hepatitis C (3); chronic periodontitis (3); hemolysis (3); hepatitis C (3); kidney stones (3); lymph node metastasis (3); multiple myeloma (3); Polycystic ovary (3); Thrombocytosis (3); acquired immune deficiency syndrome (2); acute respiratory distress syndrome (2); Alpha-thalassemia (2); Ascites (2); Ataxia (2); bacterial pneumonia (2); central nervous system tumors (2).
A further 239 diseases each share a sentence with TF in 2 papers or fewer.